NOD2 (nucleotide binding oligomerization domain containing 2)
Diseases named in the same sentence as NOD2 in open-access papers (continued):
Sharing a sentence is not in itself a finding about the gene and the disease.
infection (continued). "Since we observed a NOD2-dependent increase in CCL2, type I IFNs and circulating monocytes following MDP treatment of IAV-infected mice, we investigated whether such treatment affected populations of monocytes, neutrophils and macrophages in the lungs during the course of infection." (PMID 22590599, 2012). "In AIEC-LF82 infection, the absence of either ELMO1 or NOD2 or both resulted in a significant decline in IL-6 levels compared to C1 cells." (PMID 36694274, 2023). "Prior to infection studies, we first confirmed that the synergistic effects of combined TLR4 and NOD2 stimulation were not affected by the entrapment of PRR agonists into PLGA nanoparticles." (PMID 32927915, 2020). "W. chondrophila stimulation of CXCL8 secretion in HEK293 cells indicates that TLR2, TLR4, NOD2 and NOD1 receptors are not essential to the innate immune response to infection." (PMID 27002636, 2016). "NOD2 expression was induced in HCMV-infected cells at 96 hpi, and MDP pretreatment did not further increase NOD2 expression after infection." (PMID 26830977, 2016). "The detection of endogenous TAK1 activation in HEK293T cells following infection with wildtype, but not T3SS3 mutants, suggests the activation of the intracellular pattern recognition receptors (PRRs) NOD1 and NOD2, both of which signal through TAK1." (PMID 24884837, 2014). "During “normal” infections, however, the T3SS-1-mediated invasion seems to outweigh the alternative invasion route, leaving NOD1 and NOD2 to play a non-significant role." (PMID 24381573, 2013). "In a subsequent study using aerosol infection with 100 CFU of H37Rv, the lack of difference in bacterial burden up to 8 weeks postinfection was confirmed, but Nod2-KO mice (C57BL/6) had less pulmonary leukocyte infiltration than WT during Mtb and BCG infections." (PMID 37262021, 2023). "As NOD1 and NOD2 agonists are not released from the surface of L. interrogans due to the action of LipL21, L. interrogans is able to also escape recognition by NOD1 and NOD2 to establish an infection in the host." (PMID 35967403, 2022). "Infection of WT macrophages with N. caninum induced a marked production of IL-6 and TNF-α, and this response was partially suppressed in macrophages lacking Nod2, whereas IL-10 levels were increased in culture supernatants of Nod2−/− BMDMs at the initial replicative cycle of the parasite (8 h)." (PMID 27377650, 2016).
tumor (85 papers, 2007 to 2025). "Studies show that activation of the NOD1 pathway accelerates tumor progression, while NOD2 loss is associated with a protective effect in colitis-related tumors." (PMID 41200171, 2025). "Recent investigations have implicated NOD2 in the progression of colorectal, breast, lung, endometrial, and cervical cancers, correlating with enhanced tumor invasion, proliferation, and poor patient survival." (PMID 40868292, 2025). "Clustering of the immune components of LUAD samples in The TCGA database identified the gene encoding nucleotide-binding oligomerization domain-containing protein 2 (NOD2) as an important gene with tumor-suppressing effects." (PMID 38983267, 2024). "Lower levels of NOD2 expression are associated with unfavorable characteristics, such as larger tumor size, metastatic tumors, and advanced stages." (PMID 38983267, 2024). "Multiple tumor‐related pyroptosis signatures have also reported that high NOD2 and SCAF11 expression are associated with poor prognosis, but unfortunately, their mechanism in tumors has not been uncovered." (PMID 35651286, 2023). "Nevertheless, we found that genotype CT and TT in NOD2 rs2066844 confers 2.0- and 4.9-times higher risk to develop this tumor, respectively." (PMID 35123435, 2022). "The gene set enrichment analysis for HS578T/NOD2 revealed mostly relevant upregulated pathways, linked to translation, immune response and tumor progression pathways." (PMID 30791886, 2019). "Additionally, Western blot analysis was performed to determine NOD2 expression and its associated cyclin proteins in the tumor tissues of both groups." (PMID 39353904, 2024). "This said, the loss of Nod2 expression in neutrophils may probably improve tissue repair and tumor progression through modulation of the Th17-mediated immunity, as observed in LysMCre;Mcl1fl/fl mice." (PMID 37876927, 2023). "Loss of NOD2 may promote polarization of tumor-associated macrophages into the M2 phenotype (protumorigenic phenotype)." (PMID 35692574, 2022). "Moreover, the expressions of CASP6, GPX4, GSDMC, and NOD2 could increase the susceptibility of tumor cells to paclitaxel, 5-fluorouracil, dasatinib, and gefitinib." (PMID 35368686, 2022). "Immunofluorescence results also showed a significant enhancement of NOD2 expression in tumor tissues after DEH (40 mg/kg) treatment." (PMID 40468178, 2025). "P.g. also manipulates inflammatory signaling in SCC-25 cells by activating NF-κB and MAPK pathways, driving tumor-associated inflammation and metastasis via upregulation of CCL20, TNFAIP6, CXCL8, TNFAIP3, TRAF5, CYP1A1, and NOD2 gene expression." (PMID 40924302, 2025). "Recently, it was shown that induced MHCII+ Ly6Clo monocytes expand by NOD2-agonist treatment and were involved in anti-tumor immunity." (PMID 41244563, 2025). "We found that the high expression of NOD2 predicted poor survival rates, indicating that it functioned as a tumor-promoting gene in this study." (PMID 40761791, 2025). "To further validate the NOD2 expression in vivo, we performed an immunohistochemical analysis on tumor specimens derived from mouse xenograft models." (PMID 40868292, 2025). "These analyses corroborated the NOD2 protein expression within tumor tissues generated from GL261, U251, and U87MG cell lines." (PMID 40868292, 2025). "We found that NOD2-dependent LY6Clo I-NCMs promoted tumor immunity more potently than their N-NCM counterparts." (PMID 39545417, 2024). "In the early stages, elevated expression of NOD1 and NOD2 can activate adaptive immune responses or induce apoptosis in tumor cells." (PMID 39329913, 2024). "In contrast to the control group, the implanted NOD2 overexpression cell group more effectively suppressed the tumor growth rate and size." (PMID 39353904, 2024). "While NR4A1-dependent N-NCMs are naturally abundant under steady-state conditions in WT hosts, the NOD2-dependent subset can be pharmacologically induced to enhance tumor immunity against a variety of metastases." (PMID 39545417, 2024).
tumor (continued). "NOD2-induced I-NCMs inhibited tumor seeding and induced regression of various tumor colonies more robustly than did N-NCMs." (PMID 39545417, 2024). "In contrast, accelerated proliferation and larger tumor growth were measured in the tumors implanted into the NOD2 knockdown group of cells." (PMID 39353904, 2024). "Conversely, aberrant activation of NOD2 promotes tumor progression in hepatocellular and cervical cancers." (PMID 39353904, 2024). "The NOD2 overexpression group exhibited significantly higher levels of NOD2 expression in the tumor bodies compared to the control group." (PMID 39353904, 2024). "In vivo, the upregulation of NOD2 expression improved the autophagy level of tumor tissue and inhibited cells proliferation." (PMID 36316517, 2023). "Global pathway analysis uncovered several functional categories that are related to immune system processes among tumor specimens with the highest levels of NOD2 expression." (PMID 37876927, 2023). "They found that NOD2 acted as a tumor suppressor, as more HCC tumors were seen in the liver of NOD2-deficient mice than in the liver of NOD2-intact mice." (PMID 36268029, 2022). "In these models of experimental hepatocarcinogenesis, NOD2 acted not only as a tumor suppressor but also as a chemotherapy enhancer." (PMID 36268029, 2022). "After multiple assessments on the 13 PDEIRGs, NOD2 was considered to be the central immune gene and had a strong effect on suppressing tumour progression." (PMID 34268854, 2021). "In this model, NOD1 overexpression reduced estrogen-induced tumor proliferation, while NOD2 activation led to a remarkable suppression of tumor growth." (PMID 34899721, 2021). "In this study, we were the first to create the IPM based on the ssGSEA clustering and identified a tumour inhibitor, NOD2." (PMID 34268854, 2021). "Priming with CpG attenuated Il6 and Nlrp3 expression, further upregulated expression of Nod2, Oas2, RhoA, Pycard, Tlr1/2 and Il12, and enhanced T-cell number and activation while polarizing macrophages to an anti-tumor phenotype." (PMID 33441763, 2021). "Meanwhile, we elucidated the possible mechanism of TAM phenotypic conversion mediated by deceased NOD2 in promoting tumour development through the combination of integrated multiple omics analyses and molecular biology experiments." (PMID 34268854, 2021). "Our data supported the notion that decreased NOD2 leads to an inhibited innate immune status by mediating TAMs phenotypic conversion in the TME which contributed to tumour progression and poor prognosis of LUAD patients." (PMID 34268854, 2021). "The NOD2 expression values were calculated in the samples of 11 distant normal lungs, 11 primary tumours and 10 metastatic brain tissues." (PMID 34268854, 2021). "And the positive correlation between ITGA5, NOD2, P2RX4, RIPK2, SLC7A1 and immune score indicated that the tumor tissue in the high-risk group is highly infiltrated by immune cells, which is consistent with risk score." (PMID 33828988, 2021). "In accord with previous studies, we reported LUAD patients with decreased NOD2 had a disposition to tumour progression and bad prognosis." (PMID 34268854, 2021). "Altogether, these data indicated that NOD2 exerted the anti-tumor effect on HCC cells through its activation of autophagy-mediated apoptosis." (PMID 32144252, 2020). "Compared with the WT mice, the tumor numbers, liver body ratios, and tumor diameters in the NOD2-/- mice were significantly increased, whereas the body weights of the NOD2-/- mice were significantly decreased." (PMID 32144252, 2020). "The mice were sacrificed 24 weeks after the induction, and the tumor formation status of WT and NOD2-/- mice were analyzed and compared." (PMID 32144252, 2020). "We further validated NOD2 as a tumor suppressor as well as a potent regulator of chemosensitivity in HCC cells by directly regulating AMPK pathway." (PMID 32144252, 2020).
tumor (continued). "Further assay showed that tumors transfected with NOD2 plasmid had significantly smaller tumor volumes and lower tumor weights than those tumors transfected with the mock plasmid." (PMID 32144252, 2020). "In this study, we showed that innate immune sensor NOD2 acted as a tumor suppressor in HCC progression and inhibited hepatic tumorigenesis in vivo and in vitro." (PMID 32144252, 2020). "Further analysis of the IHC staining showed that NOD2 expression was dramatically decreased in HCC patients with advanced tumor node metastasis (TNM) stages." (PMID 32144252, 2020). "We demonstrated that NOD2 deficiency promoted hepatocarcinogenesis in N-nitrosodiethylamine (DEN)/carbon tetrachloride (CCl4) induced HCC mice model and xenograft tumor model." (PMID 32144252, 2020). "Altogether, these in vitro data further supported our data from animal models that NOD2 acted as a tumor suppressor in HCC progression." (PMID 32144252, 2020). "Altogether, these data indicated that NOD2 exerted its anti-tumor effect on HCC cells through its effective activation of AMPK pathway." (PMID 32144252, 2020). "In conclusion, we investigated the role of NOD2 in an integrate investigation system including animal model, cellular model and clinical specimen, and demonstrated that NOD2 acted as a tumor suppressor in HCC cells." (PMID 32144252, 2020). "In vitro investigation showed that NOD2 acted as a tumor suppressor and inhibited proliferation, colony formation and invasion of HCC cells." (PMID 32144252, 2020). "In consideration of the tumor suppressor role of NOD2 in animal and cellular models, all these clinical data indicated that loss of NOD2 expression in HCC patients contributed to HCC progression." (PMID 32144252, 2020). "High NOD2 and low NLRX1 expression in tumor tissue was associated with short MST (P = 0.012 and 0.014, respectively)." (PMID 28960882, 2017). "Beyond LPS, MAMP specificity at NOD sensors yields divergent outcomes: Enterococcus peptidoglycan remodeling via the secreted hydrolase SagA generates muropeptides that activate NOD2, enhance cross-presentation, and consistently improve anti-PD-L1 responses in multiple tumor models." (PMID 41339918, 2025). "Similarly, a biodegradable nanoparticle platform delivering IL-2, anti-CD28, Pam3CSK4, and a NOD2 agonist, was shown to stimulate endogenous tumor-infiltrating T cells and slow tumor growth." (PMID 40948803, 2025). "While the brain’s immune-privileged status limits the PAMP exposure, alternative endogenous ligands may activate NOD2 signaling in the tumor microenvironment." (PMID 40868292, 2025). "Administration of MDP, a NOD2 agonist, increases antitumor immunity to PD-1/PD-L1 blockade, and using blocking antibodies against PD-L2/RGMb overcomes microbiome-mediated resistance in multiple mouse tumor models." (PMID 39895632, 2025). "Similarly, treatment with DEH (40 mg/kg) increased level of NOD2 in tumor tissues of BALB/c nude mice." (PMID 40468178, 2025). "Both NOD1 and NOD2 exhibit dual effects on tumor cells, which may vary depending on the tumor type and stage." (PMID 39329913, 2024). "Conversely, heightened expression of NOD1 and NOD2 may exacerbate systemic inflammation by triggering an excessive release of inflammatory factors, thereby promoting tumor growth, metastasis, and invasion." (PMID 39329913, 2024). "SLC28A2, VIP, CMKLR1, MARCO, and NOD2 were detected at low levels in non-tumor and tumor cells." (PMID 38742117, 2024). "Moreover, DAMPs produced during paclitaxel treatment can activate the NOD2 signaling and worsen the tumor microenvironment, resisting the therapeutic effect of paclitaxel, but NOD2 antagonist enables the sensitization of chemotherapeutic response." (PMID 37324457, 2023).
tumor (continued). "Nucleotide-binding oligomerization domain 2 (NOD2) overexpression or CXCL17 knockdown NOD2 exhibited anti-tumor characteristics by activating the AMPK pathway through direct binding with the AMPKα-LKB1 complex, resulting in the increased autophagy-modulated apoptosis of HCC cells." (PMID 38003445, 2023). "Moreover, tumor cell-derived microparticles (TMPs) by oral vaccination activated NOD2 leading to subsequent antitumor T cell responses, inhibited the tumor growth of CT26 colon cancer and B16 melanoma in mice." (PMID 35413927, 2022). "Lower NOD2 gene expression was found in the LIC which was thought to have more tumour components." (PMID 34268854, 2021). "Descended expression of NOD2 indicated not only tumour progression but also poor prognosis." (PMID 34268854, 2021). "Univariate and multivariate analysis demonstrated that, apart from vascular invasion and tumor number, NOD2 expression remains as an independent prognostic factor of both OS (hazard ratio = 3.447, 95% CI: 1.931–6.154, P < 0.001) and TTR (hazard ratio = 3.010, 95% CI: 1.861–4.868, P < 0.001)." (PMID 33413510, 2021). "Thus these in vivo data indicated that NOD2 inhibited the xenograft tumor growth in HCC mice models." (PMID 32144252, 2020). "The favorable effect of NOD2 on suppressing tumor and increasing chemosensitivity of HCC is reported here for the first time, which may indicate novel therapeutic strategy against HCC based on the modulation of NOD2." (PMID 32144252, 2020). "Altogether, this study showed that NOD2 acted as a tumor suppressor as well as a chemotherapeutic regulator in HCC cells by directly activating AMPK pathway, which indicated a potential therapeutic strategy for HCC treatment by upregulating NOD2-AMPK signaling axis." (PMID 32144252, 2020). "Furthermore, it is reported that NOD2 agonists can activate the cytotoxic potential of immune cells residing in the tumor microenvironment (TME) and, consequently facilitate their engagement with cancer cells." (PMID 32144252, 2020). "Furthermore, the inhibitory effect of NOD2 on the malignant behaviors of HCC cells was also significantly rescued by blocking AMPK pathway, which indicated that NOD2 exerted the anti-tumor effect through effective activation of AMPK pathway." (PMID 32144252, 2020). "Elucidation of NOD1 and NOD2 effects on tumor cell viability and proliferation may unveil potential targets for future therapeutic intervention." (PMID 29615116, 2018). "Similarly, activation of NODs, in particular NOD2, to elicit robust cell-based anti-tumor immunity has been under scrutiny for several years." (PMID 25071785, 2014). "NOD2/CARD15 variant alleles were associated with a more advanced TNM stage; however, partly due to the small number of patients, results were not corrected for other possible confounding factors (e.g. age at diagnosis or tumor differentiation)." (PMID 17389035, 2007). "However, another study found an increased tumor incidence in NOD2 knockout mice, suggesting that the role of NOD2 in tumorigenesis may not be related to intestinal microbial imbalance." (PMID 41200171, 2025). "Dysregulation of innate pathways, exemplified by contradictory reports on NOD2, further illustrates this complexity: depending on context, such signaling may enhance immune surveillance or drive tumor progression through chronic inflammation and microbiota-related dysbiosis." (PMID 41200171, 2025). "The better survival of NOD2hi COAD patients compared to NOD2lo patients confirms the importance of NOD2 signaling in the immune response against tumor, but may appear at odds with the lower carcinogenesis observed in mice with Nod2 deficiency in lysozyme-expressing myeloid cells." (PMID 37876927, 2023). "Thus, peptidoglycans from Mycobacterium tuberculosis and NOD2 agonists could also be hot tumor inducers." (PMID 36494701, 2022).